CBS (cystathionine beta-synthase)
Diseases named in the same sentence as CBS in open-access papers (continued):
Sharing a sentence is not in itself a finding about the gene and the disease.
gastric cancer (continued). "In summary, the salient finding from this study is that CBS is suppressed by promoter methylation in colorectal and gastric cancers." (PMID 23152928, 2012). "More information is available about the relation of CBS expression in gastric cancer." (PMID 37483514, 2023). "Whether the tumor-suppressive effect of CBS in gastric cancer cells is mediated through H2S requires further investigation." (PMID 35758651, 2022). "We then detected CSE and CBS expression in human gastric cancer cells, SGC 7901 cell line." (PMID 26078811, 2015). "Indeed, the CBS promoter was methylated in all six gastric cancer cell lines tested, and half of them displayed complete absence of unmethylated CBS promoter (SNU-1, NCI-N87, and AGS) that was associated with undetectable CBS transcription." (PMID 35758651, 2022). "Interestingly, both CSE and CBS were upregulated in gastric carcinoma mucosa." (PMID 26078811, 2015). "Two specific inhibitors of CBS and CSE, aminooxyacetic acid (AOAA) and DL-propargylglycine (PAG), enhance the stronger anticancer effect of 3,3'-Diindolylmethane (DIM) in gastric cancer BGC-823 and SGC-7901 cells." (PMID 38448410, 2024). "LncRNA CBSLR affects the m6A modification of CBS by acting on YTHDF2, and high expression of CBSLR leads to poor prognosis of gastric cancer patients." (PMID 37781080, 2023). "Consistent with this concept, in human gastric cancer cells with activated PI3K/AKT signaling, we demonstrate that CBS expression is suppressed due to promoter hypermethylation." (PMID 35758651, 2022). "Low, or the absence, of correlation between EGFR dependency and expression is shown for CBS and SRM genes in rhabdoid cancer, for the MTR gene in gastric cancer and for the SRM gene in rhabdoid and neuroblastoma cancer cells." (PMID 36361596, 2022). "Taken together, we find that CBS is a novel regulator of AIS and a potential tumor suppressor in PI3K/AKT-driven gastric cancers, providing a new exploitable metabolic vulnerability in these cancers." (PMID 35758651, 2022). "Furthermore, CBS mRNA level was significantly decreased in tumors (N=406) compared to adjacent normal tissues (N=211) in gastric cancer patients, consistent with the hypothesis that CBS is a tumor suppressor in gastric cancers characterized by PI3K/AKT/mTORC1 pathway alterations." (PMID 35758651, 2022). "Our study warrants further analysis of CBS as an epigenetic biomarker for the molecular diagnosis of CRC and gastric cancer." (PMID 23152928, 2012). "Concomitantly, unmethylated CBS alleles were detected in Aza-treated and HCT116DKO cells, indicating that methylation of the CBS promoter directly leads to its silencing in CRC and gastric cancers." (PMID 23152928, 2012). "Methylation and decreased mRNA expression of CBS were detected in most CRC cell lines by methylation-specific PCR and semiquantitative RT-PCR, as well as in gastric cancer." (PMID 23152928, 2012). "We further investigated the presence of CBS promoter methylation in 96 primary CRC and 20 gastric cancer samples using MSP analysis." (PMID 23152928, 2012). "Comparison of CBS mRNA expression with DNA methylation status in a panel of 34 human gastric cancer cell lines revealed a significant negative correlation between CBS mRNA expression level and DNA methylation." (PMID 35758651, 2022). "Taken together, our study identifies CBS as a novel regulator of AIS maintenance and a potential tumor suppressor in gastric cancer pathogenesis, potentially providing a new metabolic vulnerability that can be harnessed to target PI3K/AKT/mTORC1-driven cancers." (PMID 35758651, 2022). "To test our hypothesis, we firstly collected human gastric cancer tissue samples and performed western blotting to determine the expression levels of H2S-producing enzymes CSE and CBS." (PMID 26078811, 2015). "We found that the expression of both CSE and CBS proteins was significantly higher in gastric carcinomas than in adjacent noncancerous gastric tissues (n = 10, P < 0.05)." (PMID 26078811, 2015).
gastric cancer (continued). "Furthermore, the CBS gene was frequently methylated in CRC and gastric cancer patients, thus suggesting that CBS acts as a TSG in CRC and gastric cancer being frequently inactivated by methylation." (PMID 23152928, 2012). "We demonstrated that CBS mRNA expression was absent in several colorectal and gastric cancer cell lines due to promoter methylation." (PMID 23152928, 2012). "There are some studies that have evaluated the association between malignant tumor susceptibility and polymorphisms of the CBS gene (844ins68) in CRC but not in esophageal or gastric cancer." (PMID 23152928, 2012). "The aim of the present work was to examine whether CBS was a new potential TSG and to test if CBS mRNA expression was downregulated by promoter hypermethylation in CRC, as well as in gastric cancer." (PMID 23152928, 2012). "To evaluate alteration of CBS protein expression in human gastric cancer, we assessed CBS protein levels in paired samples of gastric tumors and adjacent non-cancerous mucosa from 62 gastric cancer patients in a tissue microarray (TMA) using immunofluorescent staining." (PMID 35758651, 2022). "Blocking DNA methylation with azacitidine, a DNA methyltransferase-inhibiting cytosine nucleoside analogue upregulated CBS mRNA expression in all cell lines tested except Hs746T, whereby SNU-1 cells showed a>50-fold increase, confirming epigenetic silencing of CBS expression in gastric cancer cells." (PMID 35758651, 2022). "In parallel, a negative correlation between CBS and xCT expression was observed in gastric cancer cell lines, which is consistent with a recent report that cancer cells maintain intracellular cysteine levels and sustain cell proliferation by increasing xCT-mediated cysteine uptake." (PMID 35758651, 2022). "However, the biological consequence of CBS epigenetic silencing in gastric cancer has not been determined." (PMID 30050925, 2018).
Alzheimer disease (10 papers, 2017 to 2025). A progressive, neurodegenerative disease characterized by loss of function and death of nerve cells in several areas of the brain leading to loss of cognitive function such as memory and language. "It was noted, however, that intraventricular administration of homocysteine, a risk factor for the development of Alzheimer's disease, reduces the level of CBS expression in the rat hippocampus with simultaneous impairment of memory and learning." (PMID 37874531, 2023). "CBS is notably overexpressed in individuals with Alzheimer’s disease, indicating the possibility that some other portion of the cysteine metabolic pathway is disrupted, and an increase in CBS is a response." (PMID 31947790, 2020). "Polymorphisms in cystathionine beta synthase (CBS), which catalyzes the conversion of homocysteine to cystathionine, is well-known risk factor for Alzheimer's disease." (PMID 28177875, 2017). "Noteworthy, in the brain of Alzheimer's disease (AD) patients has been observed a dramatic decrease of CBS activity and a consequent severe reduction in H2S levels (about 55%)." (PMID 29021980, 2017). "This, however, remains to be investigated and so is the question as to whether CBS—or, more broadly, the H2S system—plays a role in the pathogenesis of plaque formation and Alzheimer’s disease (AD)–like neuropathologies in DS." (PMID 38558215, 2024). "In Alzheimer’s disease models, SPRC reduced astrogliosis, lipofuscin accumulation, and the amyloid beta 1–42/amyloid beta 1–40 (Aβ1–42/Aβ1–40) ratio through H2S-associated inhibition of NF-κB and mitogen-activated protein kinase (MAPK) signaling, while increasing CBS activity and H2S concentration." (PMID 41465271, 2025). "H2S, as an endogenous molecule produced by the enzymatic activity of CTH, CBS, or MPST, is the main regulator of post-translational S-sulfhydration (persulfidation) of proteins that has been reported, e.g., in aging, Alzheimer’s disease, or the cardiovascular system." (PMID 37627540, 2023).
liver cancer (10 papers, 2020 to 2024). An epithelial or non-epithelial malignant neoplasm that arises from the liver. "CBS and H2S have been confirmed to be involved in the development of various solid tumors, including colon, ovarian and liver cancer." (PMID 33558454, 2021). "In liver cancer cells, a previous study has shown that CBS-generated H2S can induce autophagy and apoptosis through the PI3K/Akt/mTOR pathway." (PMID 32770044, 2020). "In human liver cancer cells HepG2 and murine liver cells, CBS was found in the nucleus and the cytoplasm." (PMID 32365821, 2020). "CBS was a viable pharmacological target in liver cancer and chronic myeloid leukemia." (PMID 38172561, 2024). "Moreover, functional restoration of CBS activity in HNF4α-depleted liver cancer cells, either by supplementation of Ctt or H2S or by overexpression of CBS, significantly alleviates stress resistance, cell migration, and EMT induced by HNF4α deficiency." (PMID 32770044, 2020). "Our data further suggest that the transsulfuration pathway in SAA metabolism, particularly CBS-mediated production of Ctt and H2S, may be one of the major effectors of HNF4α-mediated EMT suppression in liver cancer." (PMID 32770044, 2020).
osteoporosis (10 papers, 2017 to 2025). A condition of reduced bone mass, with decreased cortical thickness and a decrease in the number and size of the trabeculae of cancellous bone (but normal chemical composition), resulting in increased fracture incidence. "CBS deficiency has been linked to various diseases, including osteoporosis, lens dislocation, and thrombosis." (PMID 40303407, 2025). "Collectively, these data indicate that H2S is required for normal bone homeostasis, and potentially mitigates CBS-deficiency induced osteoporosis." (PMID 30323246, 2018). "These skeletal manifestations give older patients an appearance similar to that of Marfan syndrome but CBS deficiency can be distinguished by the presence of osteoporosis." (PMID 27778219, 2017). "Deficiency in CBS activity can lead to increased concentrations of homocysteine and decreased bone quality, making chickens, and layers in particular, more susceptible to osteoporosis and bone breaks." (PMID 36837763, 2023). "CBS deficiency was associated with human and murine osteoporosis." (PMID 32183900, 2020). "Cystathionine β-synthase (CBS) deficiency, a rare metabolic disease caused by mutations in the CBS gene, is characterized by severely elevated levels of homocysteine (Hcy) and its metabolites and pathologies in the cardiovascular, skeletal (osteoporosis), and nervous systems." (PMID 32260476, 2020). "Therefore, our data strongly suggests that H2S could be a potential therapeutic agent for treating osteoporosis arisen due to CBS-deficiency through epigenetic modulation of osteogenesis." (PMID 30323246, 2018). "The newborn CBS-knockout (KO) mice who received treatment with recombinant poly ethylene glycol human truncated CBS (PEG-CBS) were rescued from osteoporosis-like symptoms." (PMID 37588196, 2024). "In patients with osteoporosis, the expression of CBS was found to be down-regulated in femur tissues, leading to a lower BMD." (PMID 37588196, 2024). "To investigate the contribution of DNA methylation in ALOX12 and CBS during osteoporosis, we performed ovariectomy to induce osteoporosis-like symptoms in rats." (PMID 37588196, 2024). "Taken together, our experiments in the rat model demonstrate that there is hypermethylation of ALOX12 and CBS, and this correlated with the presence of osteoporosis and with decreased protein expression of these targets." (PMID 37588196, 2024). "2D histological evaluation of the mouse distal femur also confirmed the decrease in trabecular bone volume in CBS+/− mice, indicating osteoporosis." (PMID 30323246, 2018). "Future research will need to be performed on the osteoclast phenotype and BMMSCs functions in CBS+/− mice to fully understand the pathobiology of epigenetic deregulation and inflammation in destructive diseases such as osteoporosis." (PMID 30323246, 2018). "Moreover, the protein expression of ALOX12 and CBS was also lower in the osteoporosis model group as indicated by Western blotting." (PMID 37588196, 2024). "Mice model of CBS KO exhibited hyperhomocystenemia and osteoporosis." (PMID 33093559, 2020). "CBS KO mice showed increased osteoclastogenesis and osteoporosis which could be mitigated by supplementation of N-acetyl cysteine." (PMID 33093559, 2020).
atherosclerosis (8 papers, 2017 to 2025). A disease characterized by the build-up of fatty material and calcium deposition in the arterial wall resulting in partial or complete occlusion of the arterial lumen. "Taken together, these findings suggested that TLR4 and CBS play key roles in the development of atherosclerosis." (PMID 36204316, 2022). "Top canonical pathways, identified by Ingenuity Pathways Analysis, such as LXR/RXR, FXR/RXR activation (− log[P-value] = 30–31) and atherosclerosis signaling (− log[P-value] = 10–11) were similarly affected in Cbs−/− mice and CBS−/− humans." (PMID 32612202, 2020). "In addition to CSE, CBS also influences atherosclerosis progression." (PMID 39156383, 2024). "Thus, CBS plays a role in both atherosclerosis and ferroptosis." (PMID 35152560, 2022). "Taken together, the levels of H2S and CSE/CBS/3-MST could serve as potential biomarkers and therapeutic targets for patients with atherosclerosis." (PMID 39156383, 2024). "Since only 2% of CBS-/-ApoE-/- mice survived up to 6 months of age, the pathophysiological relevance of CBS-/- to H2S metabolism in atherosclerosis is not clear." (PMID 29018349, 2017).
hypermethioninemia (8 papers, 2015 to 2022). "CBS deficient individuals undergoing betaine supplementation without sufficient dietary methionine restriction can develop severe hypermethioninemia and brain edema." (PMID 32154053, 2020). "In an asymptomatic, well looking newborn of normal birthweight and gestational age with persistent hypermethioninemia and plasma tHcy higher than, perhaps 100 μM, CBS deficiency becomes the presumptive diagnosis." (PMID 26289392, 2015). "Genetic mouse models of CBS-deficient HCU are characterized by normal or slightly elevated plasma Met in contrast to HCU patients, who often develop severe hypermethioninemia." (PMID 32722248, 2020). "After tHcy testing was introduced as a second-tier test for CBS, followed by Sanger sequencing as third-tier, the reporting of other causes of hypermethioninemia not included in eNBS has been avoided." (PMID 33123633, 2020).
melanoma (8 papers, 2014 to 2025). A malignant, usually aggressive tumor composed of atypical, neoplastic melanocytes. "In in vivo models of melanoma and lymphoma, antitumor T cells conditioned ex vivo with exogenous H2S or overexpressing CBS demonstrated superior tumor control upon adoptive transfer." (PMID 39546607, 2024). "Under hypoxic conditions, expression of CBS on protein level was significantly reduced in both melanoma WM115 and WM266-4 cells after 24 h of culture in hypoxia." (PMID 37892173, 2023). "In melanoma cancer cells that express more CBS than usual, Panza and colleagues identified the various types of congenital nevi (combinational, functional, and dysplastic)." (PMID 35684331, 2022). "Additionally, the biological consequences of modulating CBS expression in melanoma appear to have a minimal functional impact on cell proliferation." (PMID 41373571, 2025). "While CBS overregulation has been observed in melanoma cells, its expression is absent in dysplastic nevi, present in one out of four primary melanoma samples, and found in four out of five melanoma cell lines." (PMID 41373571, 2025). "Positive CBS expression was found in only 25% of the primary melanomas analyzed." (PMID 38250807, 2024). "More importantly, modulation of CBS expression had a minimal effect on melanoma cell proliferation." (PMID 30050925, 2018). "Hypoxia reduces the expression (mRNA/protein level) of cystathionine beta-synthase as well as thioredoxin reductase 1 and inhibits the proliferation of WM115 and WM266-4 melanoma cells." (PMID 37892173, 2023). "In this research paper, we examined the expression levels of sulfurtransferases (MPST, TST, CTH) and cystathionine beta-synthase in human primary (WM115) and metastatic (WM266-4) melanoma cell lines both in normoxic and hypoxic conditions." (PMID 37892173, 2023). "Furthermore, ADT-OH inhibits the dynamics of epithelial-mesenchymal transition (EMT), reduces cell proliferation, and restricts melanoma invasion in mice (B16F10, A375) by suppressing the CSE/CBS and FAK/Paxillin signaling pathways." (PMID 41373571, 2025). "Based on our results, we can say that in melanoma cell lines such as WM115 and WM266-4 cells, the downregulation of CBS, as well as thioredoxin reductase 1 expression, may play a significant role in inhibiting cell proliferation." (PMID 37892173, 2023). "CBS expression is absent in dysplastic nevi, detected in only 25% of primary melanoma samples, and unregulated in four of five melanoma cell lines examined." (PMID 30050925, 2018). "Therefore, as opposed to other types of cancer reviewed in this review, CBS does not appear to play an dominant role in human melanoma." (PMID 38250807, 2024). "Thus, both CBS and TXNRD1 may also be important therapeutic targets in the treatment of melanoma." (PMID 37892173, 2023). "In contrast, different human melanoma cell lines (Sk-Mel-5, Sk-Mel-28, A375, and PES 43) with normal epidermal melanocytes (NHEM) do not exhibit CBS expression." (PMID 35684331, 2022). "Additionally, upregulation of various H2S-producing enzymes (such as CSE, CBS, and 3-MST) has been observed in human skin cell lines and in malignancies like melanoma and non-melanoma skin cancers." (PMID 41373571, 2025). "An analysis of one normal human epidermal melanocytic (NHEM) cell line and four melanoma cell lines showed a very low expression of all three enzymes in the NHEM cell line, with the melanoma cell lines showing mildly increased CSE, and no changes in CBS and 3-MST expression." (PMID 35366284, 2021).